BAD (BCL2 associated agonist of cell death)
Diseases named in the same sentence as BAD in open-access papers (continued):
Sharing a sentence is not in itself a finding about the gene and the disease.
tumor (continued). "Aberrant methylation is a specific characteristic of HRK in various tumor cells that is not seen in other BH3- only family genes (BAD, BID, and PUMA) examined." (PMID 27478805, 2016). "Increased BAD expression has effects on proliferation of NSCLC cell lines and tumor growth in vivo." (PMID 23725574, 2013). "Our data suggested that increased expression of BAD enhance apoptosis and has negative influence on cell proliferation and tumor growth in NSCLC." (PMID 23725574, 2013). "Although both increased proliferation and glycolysis are hallmarks of tumor growth, the experimental evidence that connects BAD expression with tumor growth has been lacking." (PMID 19593445, 2009). "Moreover, DFFB deletion in tumor cells may attenuate killing by granzymes, as inactive DFFB is cleaved and activated by granzymes B and M. BAD/BAX deletions in tumor cells may also blunt rapid killing by granzyme B, which activates BAX and caspase-3." (PMID 41175874, 2025). "In contrast, a lack of BAD expression correlates with lymph node metastasis and higher tumor grade." (PMID 37686282, 2023). "Thus, wild-type BAD stimulated cell and tumor growth through an alternative pathway that did not require S118 phosphorylation, 14-3-3 binding or Bcl-XL interactions." (PMID 30635657, 2019). "BAD promotes cell death, and TNFSF14 protein stimulates the proliferation of T cells and trigger apoptosis of tumor cells—while TNFAIP8 acts as the negative mediator of apoptosis." (PMID 36839713, 2023). "As BAD-LAMP levels correlated with the dysfunctional status of TA-pDCs, we examined the consequences of treating pDCs in vitro with tumours supernatants (snTUM) known to have or not immunosuppressive activity." (PMID 29030552, 2017). "Surprisingly, overexpression of BAD was found to be an independent negative prognostic factor for DFS, suggesting that dysregulation of pro-apoptotic signaling may contribute to aggressive tumor behavior." (PMID 41514585, 2025). "However, unlike other tumor cell contexts, where suppression of mTORC1 has been shown to reduce MCL-1 expression, our analysis of GCB-DLBCL cells reveals an unpredicted mechanism of synergy wherein suppression of AKT induces mitochondrial accumulation of BAD and BIM." (PMID 26460954, 2015).
infection (11 papers, 2015 to 2025). The state of being infected such as from the introduction of a foreign agent such as serum, vaccine, antigenic substance or organism. "A subtly reduced Mx1 and ISG15 induction was seen after infection with BAD-ΔUS2,3,6,11 and BAD-ΔUS2,3,6." (PMID 40143353, 2025). "BAD is a Bcl2-associated agonist that promotes cells death, and S140 phosphorylation was upregulated in this protein following SVA infection by 1.68-fold relative to controls." (PMID 35154063, 2022). "Inhibition of EGFR abolished both AREG- and infection-induced increases in pBAD, suggesting that phosphorylation of BAD is induced by EGFR-mediated signaling." (PMID 32082070, 2019). "After 4 hours post infection, the macrophages were exposed to campothecin or thapsigargin and the phosphorylation of BAD protein in lysates was determined through western blot." (PMID 30036391, 2018). "In case of L. donovani infection, BAD phosphorylation was found to be increased in infected as well as infected H2O2-treated RAW 264.7 macrophages with a maximum at 6 h post infection (5.6- and 5.5-fold increase over control, P<0.001)." (PMID 28690843, 2017). "In L. donovani infection also, BAD phosphorylation is mediated by SHP2, as the decrease in infection-induced BAD phosphorylation by agonist treatment could be partially reversed by using SHP2 inhibitor (2.3-fold increase, P<0.001)." (PMID 28690843, 2017). "Hence, PERK inhibition decreases infection induced BAD phosphorylation." (PMID 30036391, 2018). "We wondered whether polymicrobial infection stimulates BAD pro-apoptotic activity." (PMID 29795446, 2018). "For example, PIM2 can also phosphorylate BAD, and we have shown that PIM2 expression is upregulated by LVS infection." (PMID 35873156, 2022). "Infection-induced PD-1 downregulation led to the activation of AKT resulting in phosphorylation and subsequent inhibition of proapoptotic protein BAD." (PMID 28690843, 2017). "Since we demonstrated that both ERK1/2 and Akt phosphorylations are induced by infection-mediated activation of EGFR, we wanted to investigate whether these signaling events mediate phosphorylation of the protein BAD through AREG signaling." (PMID 32082070, 2019). "Besides, the study showed that in the context of infection, the death receptor PD-1 remains repressed to facilitate sustenance of infection-induced activation of pro-survival AKT and inhibition of proapoptotic BAD thus favoring parasite survival." (PMID 28690843, 2017). "On the other hand, proapoptotic proteins BAD and BAX have not shown changes in their protein expression after infection with sh-RUNX2." (PMID 36510562, 2022).
neurodegenerative disease (4 papers, 2013 to 2024). A disorder of the central nervous system characterized by gradual and progressive loss of neural tissue and neurologic function. "BAD is associated with cellular apoptosis, a process implicated in AD and other neurodegenerative diseases, and the observed upregulation of BAD protein expression in AD brains suggest its potential as a therapeutic target." (PMID 39392404, 2024). "Results on metabolic pathways support an alteration of the Neurodegenerative Diseases and Nervous system C2 classes with the most frequently associated differentially expressed genes in the BSP (BAD, NEFH, NDUFB2, DERL1, NEFL)." (PMID 23782433, 2013).
adenocarcinoma (2 papers, 2013 to 2023). A common cancer characterized by the presence of malignant glandular cells. "BAD overexpression alone induces cell apoptosis, and depressed cell proliferation and cell growth depends on cell types, especially in adenocarcinoma." (PMID 23725574, 2013). "All these indicated that BAD play a negative role in specific cell types, especially in adenocarcinoma cells." (PMID 23725574, 2013).
head and neck tumors (1 paper, 2019). "Our data shows for the first time in head and neck tumors that, in the absence of PI3K/AKT, BAD is not phosphorylated, suggesting that BAD is phosphorylated by PI3K/AKT also in these tumors, a finding in accordance with the current literature." (PMID 31759362, 2019).
psychiatric diseases (1 paper, 2022). "First, recent genetic studies indicate that dysregulated developmental profiles of voltage-gated cation channels are highly associated with psychiatric diseases and that BCL-2 family member BAD indeed regulates potassium channels to control cell excitability and action potential generation." (PMID 36163151, 2022).
BAD also shares sentences with these, for which no sentence is quoted: Alzheimer disease (2 papers); myeloid leukaemia (2); myocardial ischemia (2); Parkinson disease (2); acne vulgaris (1); adenoma (1); amyotrophic lateral sclerosis (1); atrial septal defect (1); autoimmune disease (1); B-cell lymphoma (1); breast fibroadenoma (1); carcinoma in situ (1); cardiac hypertrophy (1); cardiomyopathy (1); cholestasis (1); Crohn disease (1); depression (1); ductal carcinoma in situ (1); Fanconi anemia (1); Friedreich ataxia (1); gastrointestinal tumors (1); hemangioma (1); hematological malignancies (1); Hyperinsulinemia (1); hypothyroidism (1); infectious disease (1); invasive breast carcinoma (1); invasive ductal carcinoma (1); kidney tumors (1); lymphoid leukaemia (1).
A further 22 diseases each share a sentence with BAD in 1 paper.